TREM2 (triggering receptor expressed on myeloid cells 2)
Diseases named in the same sentence as TREM2 in open-access papers (continued):
Sharing a sentence is not in itself a finding about the gene and the disease.
neurodegenerative disease (continued). "We propose that phagocytosis of protein aggregates by microglia is likely to be therapeutic and enhanced by TREM2 signalling, making phagocytosis of protein aggregates by microglia an important focus for future translational research in ALS and other neurodegenerative diseases." (PMID 28302159, 2017). "As neuroinflammatory processes such as microglial activation and cytokine generation are commonplace in multiple neurodegenerative diseases such as AD,22, 54 modulation of PS1/TREM2 trafficking may present alternative targeting strategies to treat AD." (PMID 29611543, 2017). "Despite this reliance on TREM2 in AD, DAM appear across other neurodegenerative diseases in which TREM2 may not be a critical player." (PMID 39564189, 2024). "Each of these ligands is involved in neurodegenerative disease; however, there remains no documentation as to whether α-syn is a ligand for TREM2." (PMID 36768798, 2023). "While increasing evidence indicates that ITAM/ITIM-containing immune receptors (i.e., TREM2, CD33, and CD22) are critically involved in AD progression, we still lack in-depth knowledge of the intracellular signaling molecules employed by these immune receptors to influence neurodegenerative disease." (PMID 37276426, 2023). "TREM2 is a pivotal gene in microglia functioning and shaping DAM, and thus, dissecting the expression profile of the TREM2 gene, including its non-coding RNA isoforms, adds significant information to the process of microglia activation and neuroinflammation in neurodegenerative diseases." (PMID 35887031, 2022). "Pharmacological targeting of TREM2 to suppress the inflammatory response and modifying ApoE ɛ4 isoform via CRISPA/cas9 may provide a new approach for developing therapeutic strategies in the treatment of neuroinflammation and other neurodegenerative diseases." (PMID 30909239, 2019). "Although the functional consequences of these variants remain to be established, such findings pave the way to inquire alternative disease risk mechanisms and may therefore further our understanding of the role of TREM2 in LOAD and other neurodegenerative diseases." (PMID 25886450, 2015). "Regardless of the detailed mechanism by which Akt is involved in TREM2-mediated M2 polarization, HA as a non-drug treatment permits an extended effort to allow for more cytoprotective signals related to microglial immune responses in neurodegenerative diseases." (PMID 32009907, 2019). "Increased peripheral TREM2+ expression and nonclassical monocytes combined with reductions in classical monocytes and CD16+ NK cells may represent a protective effect in neurodegenerative disease, while the opposite patterns may contribute to accelerated clinical decline." (PMID 39472664, 2025).
cancer (130 papers, 2016 to 2026). A tumor composed of atypical neoplastic, often pleomorphic cells that invade other tissues. "Altogether we found that the addition of CD137 agonist to GVAX and anti-PD1 is associated cancer cells and CAFs activating TREM2 signaling in TAMs." (PMID 39811671, 2025). "In a variety of cancers, infiltration of TREM2+ myeloid cells is associated with the formation of an immunosuppressive microenvironment." (PMID 38725629, 2024). "TREM2 has been linked to cancer and neurodegeneration, with therapies targeting TREM2 showing promise in these areas." (PMID 39149674, 2024). "A recent study identified the infiltration of TREM2+ LAMs as an event associated with cancer development." (PMID 38302493, 2024). "The lipid-associated TREM2 (Triggering Receptor Expressed on Myeloid Cells 2) receptor has been recently associated to mono-derived TAM in many cancer subtypes." (PMID 37342322, 2023). "As Trem2+ populations are heterogeneous and have been shown to regulate epithelial stem cell functions in normal non-cancer-associated processes, we interrogated the unique properties of Trem2+ macrophages in BCCs30." (PMID 37164949, 2023). "TREM2+ macrophages were recently reported to be highly enriched and associated with immunosuppression in various cancer types." (PMID 35746551, 2022). "Our data demonstrate that levels of immune cell infiltration were significantly associated with TREM2 expression in most types of cancer." (PMID 33679809, 2021). "To study the association between TREM2 expression level and prognosis, we performed a survival association analysis for each cancer, including OS, DSS, DFI, and PFI." (PMID 33679809, 2021). "Here, we performed an integrative multi-omics analysis across seven digestive cancer types and identified a conserved four-gene signature-DCN, COL10A1, CTHRC1, and TREM2-that is consistently enriched in matrix cancer-associated fibroblasts (mCAFs) and myeloid cells." (PMID 41977392, 2026). "High TREM2 expression is associated with poorer outcomes in various cancers, including HCC." (PMID 40918134, 2025). "TREM2+ macrophages are enriched in several human cancers and are associated with immunosuppression." (PMID 39113887, 2024). "In clear cell renal cancer, C1Q+TREM2+APOE+ TAMs were associated with cancer recurrence." (PMID 38303024, 2024). "Anti-TREM2 monoclonal antibody treatment prior to PD-1 immunotherapy that made tumors more susceptible and increase the efficacy of the former drug in different cancer types, including glioblastoma." (PMID 37335084, 2023). "Although these data are limited to HCC, they open up the prospect that activated cancer-associated fibroblasts in other cancer types may express TREM2, and in doing so may modulate paracrine signaling to the surrounding cells." (PMID 36119485, 2022). "Further, TREM2 is positively or negatively associated with prognosis in different cancers." (PMID 33679809, 2021). "Moreover, dysregulation of macrophage lipid handling and the lipid scavenger receptor, TREM2, have been implicated as key features in numerous diseases, such as Alzheimer’s, cancer, and infection – expanding the importance of our findings to additional immunological diseases." (PMID 35618862, 2022). "We find a strong correlation between TREM2 upregulation and adverse clinical outcomes in these cancers." (PMID 41681832, 2026). "Unfortunately, recent clinical evidence indicates that therapeutic TREM2 blockade has suboptimal efficacy in cancer patients." (PMID 41562407, 2026). "Deconvolution of bulk RNA sequencing (RNA-seq) data reveals high content at baseline in cancer cells, immunosuppressive cancer-associated fibroblasts, FOXP3+ CD4+ regulatory T lymphocytes, and TREM2+ macrophages." (PMID 41519129, 2026). "TREM2, upregulated in TAMs across cancers, limits PD-1 blockade efficacy; anti-TREM2 antibodies are under clinical evaluation." (PMID 40936918, 2025).
cancer (continued). "TREM2+ macrophages are often enriched in immune-excluded or “cold” tumors, but their distribution and functional role vary greatly across cancer types and patient populations, complicating patient selection and trial design clinically." (PMID 40821795, 2025). "This study elucidates the mechanism by which TREM2 shapes the immunosuppressive microenvironment and promotes tumorigenesis, highlighting TREM2 as a target for cancer immunotherapy." (PMID 41114464, 2025). "Given the critical role of TREM2 in chronic inflammation and cancer immunosuppression, it was included for further analysis." (PMID 40162859, 2025). "Under various pathological conditions, such as infection, inflammation, and cancer, the expression and function of TREM2 often undergo significant changes." (PMID 40242752, 2025). "Overall, we discovered that TREM2 overexpression on TAMs promotes GC advancement, indicating TREM2’s role as a potent driver for GC progression via its interaction with cancer cells." (PMID 41253786, 2025). "Despite the promising effects of TREM2 targeting in cancer, in obese cancer patients with metabolic disorders, TREM2+ TAM targeting can lead to adverse effects." (PMID 39516356, 2024). "The expression of TREM2 varies across different cancers and generally correlates with poor prognosis when upregulated, indicating its potential as a target for therapeutic intervention." (PMID 39697329, 2024). "As far as we know, this study represents the first investigation to document that TREM2 affects TAMs infiltration by regulating the chemotactic axis, paving the way for new therapeutic avenues to inhibit cancer development." (PMID 39135069, 2024). "Trem2 is highly expressed mainly in TAMs and has been widely studied in various malignant tumors, including breast cancer, ovarian cancer, hepatocellular carcinoma, colorectal cancer, clear cell renal carcinoma and lung adenocarcinoma." (PMID 38750472, 2024). "The identification of distinct TAM phenotypes expressing TREM2 and their differential impact on cancer prognosis opens new avenues for precision medicine approaches and personalized treatment strategies." (PMID 38972873, 2024). "Increased amounts of specific TAM subsets identified by CD163, CD206, stabilin-1, and TREM2 biomarkers correlate with both hematogenous and lymphatic metastasis in all cancer types studied." (PMID 39516356, 2024). "These distinct predictions underscore the context-dependent variations in the immune microenvironment and the nuanced role of TREM2-expressing macrophages in different cancer types." (PMID 38972873, 2024). "Katzenelenbogen discovered novel Arg1+Trem2+regulatory myeloid cells through single-cell RNA sequencing, revealing an immunosuppressive role of TREM2 in cancer." (PMID 38779685, 2024). "TREM2 is highly expressed on TAMs in a variety of cancers, including colorectal, triple-negative breast, and pancreatic cancers, and is negatively correlated with survival, and is a pro-tumorigenic marker for TAMs in mouse models and human tumors." (PMID 38725629, 2024). "For example, substantial evidence confirm a prominent immunosuppressive impact of TREM2 in cancer cells." (PMID 37335084, 2023). "TREM2 is shown to facilitate the clearance of cancer and damaged neuronal cells by macrophages and microglia." (PMID 37483607, 2023). "The molecule triggers TREM2-related maturation of dendritic cells (DCs) and has shown promising adjuvant activity in a cancer vaccine model." (PMID 36865548, 2023). "Further investigation was also done by TIMER for various cancer types, to evaluate the correlation between the immune infiltration levels and TREM2 gene expression." (PMID 36741909, 2023). "In cancer research, TREM2 is observed in macrophages beyond 200 cancer cases of humans in fostering an immune-suppressive TME." (PMID 36844870, 2023). "TREM2 expression is significantly upregulated in TAMs in the lungs of patients with cancer compared to that in healthy controls." (PMID 37563723, 2023).
cancer (continued). "Recent reports highlight a novel role for the apolipoprotein E (APOE)-TREM-2 axis in cancer, providing promising novel therapeutic targets." (PMID 36161514, 2023). "Although the mechanism of Trem2-/- KO or blockade activity seems to be T cell dependent, it remains to be elucidated the blocking effect of Trem2 as lipid marker in cancers." (PMID 37342322, 2023). "We were interested in SIRPα, MERTK and TREM2 because of their roles in the phagocytosis of cancer and apoptotic cells." (PMID 37483607, 2023). "Recently, triggering receptor expressed on myeloid cells 2 (TREM2) has been identified as a specific marker of TAMs in different human cancer models including HCC." (PMID 36831649, 2023). "By utilizing integrated technology coupling single-cell RNA sequencing and intracellular protein activity in a murine cancer model, Katzenelenbogen also clearly demonstrated the highly correlated relationship between Trem2 and Arg1." (PMID 37029450, 2023). "A greater understanding of the direct interactions between APOC1, APOE, RAB42, and TREM2 in cancer is, however, required due to the paucity of studies in this area." (PMID 36908705, 2023). "Although most of the information about TREM2 are from microglia in central nervous system, TREM2 is expressed in TAMs and seems to play an immunosuppressive role in cancer." (PMID 36359228, 2022). "We will discuss the TREM2+ macrophage signature in human cancers and the contribution of TREM2 to TAM phenotype and function." (PMID 35746551, 2022). "Tumors are comprised of a heterogeneous milieu of cells and TREM2 can be expressed by the cancer cells or by other immune cell populations such as TAMs." (PMID 36119485, 2022). "Gene expression data and protein-level data from IHC demonstrate differences in TREM2 expression between cancer types with the highest expression in glioblastoma multiforme and the lowest in acute myeloid leukemia." (PMID 36119485, 2022). "TREM2 expression is restricted within the majority of normal tissue, whereas approximately 75% of cancer types have been shown to express TREM2, making it a suitable target given its wide therapeutic window." (PMID 36031601, 2022). "Reg-TAMs most closely resemble M2-like macrophages with an immunosuppressive function regulated by triggering receptor expressed on myeloid cells 2 (TREM2) with characteristics dependent on the signature genes induced in specific cancers." (PMID 36338705, 2022). "Several studies suggest that high TREM2 expression correlates with worsened outcomes in various cancers, including gastric cancer, glioma, and renal cell carcinoma." (PMID 35359989, 2022). "With these varying results, it is of the utmost importance to continue to uncover the role of TREM2 in cancer." (PMID 36119485, 2022). "This highlights the heterogeneity of human tumors as well as the need for further investigation and understanding of the role of TREM2 in cancer." (PMID 36119485, 2022). "Although few clinical studies of TREM2 targeting in cancer are currently being conducted, the potential for developing clinical applications of TREM2-targeted therapies remains high in the short-term future." (PMID 35875168, 2022). "Collectively, although there are many factors affecting TAM transcriptional signature (i.e., tissue, disease stage, treatment, methodology), TREM2 clearly emerges as a core gene of immunosuppressive TAMs across numerous cancer types." (PMID 35746551, 2022). "This same association has also been shown in gastric cancer, colorectal cancer (CRC), triple negative breast cancer and luminal breast cancer, suggesting TREM2 contributes to oncogenic activity in these cancer types." (PMID 36119485, 2022). "Recent studies on infection and cancer highlighted a role of Trem2 in the immune evasion of pathogens and cancer cells." (PMID 33557250, 2021). "Nevertheless, most research studies into the role of TREM2 in tumors to date have been limited to a specific type of cancer." (PMID 33679809, 2021).
cancer (continued). "Our results reveal that, in DLBC, LAML, and THYM, TREM2 expression was significantly positively correlated with immune scores, as well as with stromal scores in pan-cancer analysis, except for in CHOL, DLBC, MESO, and LAML." (PMID 33679809, 2021). "Further, TREM2 was a high-risk gene in KIRC, LGG, and LIHC, while it was a low-risk gene in other types of cancer, particularly DBLC (hazard ratio = 0.3000)." (PMID 33679809, 2021). "In this study, we examined the expression of the pro-inflammatory receptor TREM-1 and the anti-inflammatory receptor TREM-2 on myeloid cells in the periphery and tumors of mice and patients with cancer." (PMID 35223446, 2021). "Further, our study explored the relationship between TREM2 promoter methylation and cancer for the first time." (PMID 33679809, 2021). "Given the newly identified role for the TREM2/ApoE axis in cancer, care should be taken when evaluating those therapies that enhance TREM2, in order to prevent unwanted effects on immunosuppressive myeloid cells." (PMID 33823896, 2021). "Up to now, the role of TREM2 in the treatments of malignant tumors is poorly understood, because relevant studies are relatively few, and most of the results are published in recent years." (PMID 34539652, 2021). "We also compared TREM2 expression levels between cancer and matched normal samples from 33 cancers, based on TCGA data." (PMID 33679809, 2021). "Our study demonstrated that TREM2 expression is correlated with TMB in 12 cancer types and with MSI in 12 cancer types." (PMID 33679809, 2021). "Our research shows that the TREM2 gene is highly expressed in 16 types of cancer, and IHC analysis confirms this tendency at the protein level." (PMID 33679809, 2021). "The team has first established the functional significance of TREM2 in cancer by using TREM2−/− mice which significantly attenuated the growth of MCA-induced sarcoma, colorectal, and mammary tumors." (PMID 33173037, 2020). "While some studies found the protective role of TREM-2 in cancer, others showed its protumorigenic potential." (PMID 32684831, 2020). "MRNA of Arginase1, CD206, Trem2 (triggering receptor expressed on myeloid cells 2) and Ym1, which are typical M2 markers, were significantly reduced upon embelin treatment at carcinoma stage (day 85)." (PMID 26799669, 2016). "Accumulating evidence has revealed the immunosuppression role of TREM2+ TAMs in several cancers." (PMID 41253786, 2025). "Within our data, we found expression of SEMA6D (semaphorin 6D) by cancer cells, a ligand of TREM2 involved in axon guidance, suggesting that cancer cells may serve as a source of instigating ligands in this signaling pathway." (PMID 39811671, 2025). "TREM2 can negatively regulate antitumor immunity by inhibiting T cell proliferation and other immune responses, making TREM2 a potential target for improving the efficacy of cancer immunotherapies." (PMID 40585251, 2025). "Future directions for TREM2 inhibition include identifying predictive biomarkers for response, optimizing combination regimens, and expanding indications to other immunologically resistant cancers." (PMID 40821795, 2025). "The combination of therapies targeting TREM2 with immune checkpoint blockade using anti-PD-1 or anti-PD-L1 antibodies may enhance therapeutic effects in various cancers." (PMID 39838454, 2025). "Likewise, TREM2 is also in higher expression in tumors across various pathological grading than that in normal tissue, according to the cancer genome atlas (TCGA) database." (PMID 39744236, 2025). "The role of TREM2 in cancer is complex and context dependent." (PMID 40385641, 2025). "However, TREM2 paradoxically switches to a tumorigenic role in most cancers, where it contributes to cancer progression and aggression." (PMID 40242752, 2025). "Strategies that aim to activate TREM2 may restrict inflammatory injury and tumorigenesis in early stages but will suppress the antitumor immune response and drive cancer progression in later stages." (PMID 39838454, 2025).